NECAP1 (NECAP endocytosis associated 1)
Description:
Involved in endocytosis.
Synonyms: DKFZP566B183; DEE21; EIEE21
Tractability: Antibody: UniProt places it where antibodies can reach, with medium confidence; its Gene Ontology location is reachable by antibodies, with medium confidence. PROTAC: ubiquitination databases record sites on it; its protein half-life has been measured.
Gene: Protein-coding gene on chromosome 12 (8,076,939 to 8,097,881, forward strand). Ensembl gene ENSG00000089818.
Subcellular location: Cytoplasmic vesicle, clathrin-coated vesicle membrane; Cell membrane
Subcellular location (Human Protein Atlas): Vesicles; Cytosol
Pathways (Reactome):
Vesicle-mediated transport: Cargo recognition for clathrin-mediated endocytosis; Clathrin-mediated endocytosis; Golgi Associated Vesicle Biogenesis
Gene Ontology:
Molecular function: protein binding
Biological process: vesicle-mediated transport; endocytosis; presynaptic endocytosis
Cellular component: clathrin vesicle coat; cytosol; clathrin-coated pit; clathrin-coated vesicle membrane; membrane; plasma membrane; presynapse
Genetic constraint (gnomAD): Loss-of-function variants: 13 observed, 34.81 expected, observed/expected ratio (o/e) 0.37, 90% interval 0.24 to 0.59. The upper end of that interval is the gene's LOEUF score, 0.59, which puts it in group 2 of 6, group 1 being the genes least tolerant of losing a copy. Missense variants: 272 observed, 363.22 expected, observed/expected ratio (o/e) 0.75, 90% interval 0.68 to 0.83. Synonymous variants: 109 observed, 132.54 expected, observed/expected ratio (o/e) 0.82, 90% interval 0.7 to 0.96.
Gene-disease validity (ClinGen):
ClinGen rates the evidence that NECAP1 causes each of these diseases.
genetic developmental and epileptic encephalopathy (autosomal recessive): Moderate. A complex neurodevelopmental disorder characterized by a range of developmental delays and epileptic encephalopathy phenotypes.
Homologues: Orthologues: chimpanzee NECAP1 (99% identical), macaque NECAP1 (98% identical), dog NECAP1 (95% identical), guinea pig NECAP1 (94% identical), mouse Necap1 (94% identical), rabbit NECAP1 (94% identical), rat Necap1 (93% identical), pig NECAP1 (85% identical), zebrafish necap1 (67% identical), tropical clawed frog necap1 (49% identical). Paralogues in human: NECAP2 (61% identical).
Diseases named in the same sentence as NECAP1 in open-access papers:
NECAP1 is named in the same sentence as 7 diseases in open-access papers, as found by Europe PMC text mining. Sharing a sentence is not in itself a finding about the gene and the disease. The quoted sentences say what the papers report.
epilepsies (2 papers, 2022 to 2025). "Mutations in NECAP1 have been correlated with syndromic epilepsies." (PMID 40243843, 2025).
infantile epileptic encephalopathy (2 papers, 2019 to 2021). an epileptic condition characterized by epileptiform abnormalities associated with progressive cerebral dysfunction. "A nonsense mutation in NECAP1 has previously been associated with a recessive early infantile epileptic encephalopathy (EIEE) in humans." (PMID 31117272, 2019).
retinal degeneration (2 papers, 2019 to 2026). Degeneration of the retina. "We hypothesize that NECAP1 is associated with retinal degeneration and is the cause of PRA in our GS study, despite the absence of any epileptic or neurological signs." (PMID 31117272, 2019). "Despite this, evidence discussed suggests NECAP1 is a provocative candidate gene for retinal degeneration." (PMID 31117272, 2019). "This study, in parallel with the known function and well-documented role of NECAP1 in clathrin-mediated endocytosis in retinal cells, presents NECAP1 as a novel candidate gene for retinal degeneration in dogs and other species." (PMID 31117272, 2019). "Our study presents further possibilities to explore NECAP1 involvement in canine and human retinal degenerations." (PMID 31117272, 2019). "This study, in parallel with the known retinal expression and role of NECAP1 in clathrin mediated endocytosis (CME) in synapses, presents NECAP1 as a novel candidate gene for retinal degeneration in dogs and other species." (PMID 31117272, 2019). "Although there is no direct functional evidence supporting the involvement of NECAP1 on retinal function, mutations discussed in endolysomal trafficking genes with similar molecular mechanisms to NECAP1 suggest this is a provocative novel candidate gene for retinal degeneration." (PMID 31117272, 2019). "Through WGS a quartet of GS dogs (two full-siblings and both parents), we have identified a novel candidate missense variant in NECAP1; this gene has not formerly been implicated in retinal degenerations in any species." (PMID 31117272, 2019). "To date, NECAP1 has not been associated with retinal degeneration in any species." (PMID 31117272, 2019). "Currently, there are no reports of NECAP1 implicated in retinal degeneration in any species." (PMID 31117272, 2019).
NECAP1 also shares sentences with these, for which no sentence is quoted: early infantile epileptic encephalopathy (2 papers); Retinal atrophy (2); infection (1); Stroke (1).